SPECC1L-ADORA2A (SPECC1L-ADORA2A readthrough (NMD candidate))
Gene: Protein-coding gene on chromosome 22 (24,270,898 to 24,442,356, forward strand). Ensembl gene ENSG00000258555.
Genetic constraint (gnomAD): Missense variants: 882 observed, 1,113.1 expected, observed/expected ratio (o/e) 0.79, 90% interval 0.75 to 0.84. Synonymous variants: 393 observed, 403.07 expected, observed/expected ratio (o/e) 0.98, 90% interval 0.9 to 1.06.